C1GALT1 (core 1 synthase, glycoprotein-N-acetylgalactosamine 3-beta-galactosyltransferase 1)
Diseases named in the same sentence as C1GALT1 in open-access papers (continued):
Sharing a sentence is not in itself a finding about the gene and the disease.
lung carcinoma (4 papers, 2018 to 2024). "In summary, the present study demonstrated the significant role of C1GALT1 in lung cancer progression and its association with poor prognosis." (PMID 38662050, 2024). "Although C1GALT1 is associated with the occurrence, metastasis, and prognosis of various malignancies, the clinical significance, biological function, and regulatory mechanism of C1GALT1 in lung cancer are poorly understood." (PMID 34307388, 2021). "Conversely, the overexpression of C1GALT1 had the opposite effect, enhancing radioresistance in these lung cancer cell lines." (PMID 38662050, 2024). "To elucidate the role of C1GALT1 in the DNA damage response of lung cancer cells, we quantified the number of γ-H2AX foci post-irradiation." (PMID 38662050, 2024). "The present study aimed to investigate the role of C1GALT1 in modulating radiosensitivity in lung cancer cell lines." (PMID 38662050, 2024). "Because radiotherapy is an important option for the treatment of lung cancer, the present study further explored the relationship between the C1GALT1 expression and radiosensitivity in A549 and H1299 cells." (PMID 38662050, 2024). "To explore the expression pattern of C1GALT1 in lung cancer, we performed bioinformatics analysis using the TCGA database." (PMID 34307388, 2021). "In this study, we comprehensively assessed the biological function of C1GALT1 in lung cancer using bioinformatics tools and clinical samples." (PMID 34307388, 2021). "Second, our study has confirmed that C1GALT1 could regulate DNA repair, cell proliferation, cell cycle regulation, and EMT, which are potentially associated with radioresistance in lung cancer cells." (PMID 38662050, 2024). "However, the role of C1GALT1 in lung cancer remains poorly understood." (PMID 34307388, 2021). "However, the role of C1GALT1 in lung cancer remains unclear." (PMID 34307388, 2021). "First, while the preliminary results of our current in vitro experiments suggest that C1GALT1 plays a crucial role in promoting radioresistance in lung cancer cells, the absence of in vivo experiments is a notable limitation." (PMID 38662050, 2024).
lymph node metastasis (4 papers, 2020 to 2024). "The present study revealed that high expression of C1GALT1 in LUAD is associated with lymph node metastasis and poor prognosis." (PMID 38662050, 2024). "The results from tissue microarray analysis demonstrated that high C1GALT1 expression was significantly associated with lymph node metastasis and advanced T stage." (PMID 38662050, 2024). "Univariate analysis identified four factors associated with prognosis: TNM stage, lymph node metastasis, tumor recurrence, and C1GALT1 expression." (PMID 34452648, 2021). "Furthermore, high C1GALT1 expression was associated with aggressive behavior (higher T stage and lymph node metastasis) in LUAD and was an independent prognostic risk factor for overall survival." (PMID 38662050, 2024). "High expression of C1GALT1 was correlated with lymph node metastasis, advanced T stage, and poor survival, and was an independent risk factor for overall survival." (PMID 38662050, 2024). "Elevated expression of C1GALT1 protein was closely associated with advanced TNM stage, lymph node metastasis, tumor recurrence, and poor overall survival." (PMID 34452648, 2021). "C1GALT1 expression was significantly associated with TNM stage, lymph node metastasis, and tumor recurrence." (PMID 34452648, 2021). "The present study aimed to assess the clinical significance of C1GALT1 in LUAD using a combination of public databases and clinical tumor samples and found that high C1GALT1 expression in LUAD tissues was associated with lymph node metastasis and poor prognosis." (PMID 38662050, 2024). "Moreover, C1GALT1 expression was closely related to lymph node metastasis and TNM stage." (PMID 34307388, 2021).
prostate carcinoma (4 papers, 2018 to 2025). A carcinoma that arises from epithelial cells of the prostate gland. "In prostate cancer, most of the genes that were overexpressed in metastasis of prostate cancer were mainly positively associated with C1GALT1." (PMID 40548474, 2025). "Overexpression of C1GalT1 is also associated with poorer prognosis and low survival in patients of colon, breast, esophageal and laryngeal, head and neck, lung, and prostate cancers." (PMID 34944925, 2021). "Immune profiling revealed context‐dependent correlations: C1GALT1 negatively correlated with Tregs and MDSCs in gastrointestinal cancers but positively in lung, breast, and prostate cancers." (PMID 40548474, 2025). "On the other hand, in kidney clear cell carcinoma, head and neck, thyroid, breast, and prostate cancers, normal tissue had higher expression of C1GALT1 than tumor tissues." (PMID 40548474, 2025). "The AR gene showed a positive correlation with C1GALT1 expression not only in prostate cancer but also in other cancer types, including pancreatic, rectal, kidney‐clear cell, head and neck, thyroid, testicular, glioblastoma, melanoma, and liver cancers." (PMID 40548474, 2025). "In prostate cancer cells, C1GALT1 regulates EGFR O-glycosylation to enhance galectin-4-mediated phosphorylation of EGFR." (PMID 29930379, 2018). "C1GALT1 expression was significantly upregulated in gastrointestinal and genitourinary cancers compared to normal tissues, while downregulated in thyroid, breast, and prostate cancers." (PMID 40548474, 2025). "Similarly, PTEN was positively correlated with C1GALT1 expression in prostate cancer as well as in pancreatic, colon, rectal, cervical/endocervical, bladder, kidney‐clear cell, head and neck, thyroid, breast, liver cancers, and melanoma." (PMID 40548474, 2025). "The reason that C1GALT1 exhibits different effects on EGFR in prostate cancer and HNSCC cells could be due to cell-specific differential O-glycosites on EGFR." (PMID 29930379, 2018). "It was reported that C1GALT1 knockdown decreases galectin-4-mediated but not ligand-mediated EGFR phosphorylation and downregulates EGFR protein levels in prostate cancer cells." (PMID 29930379, 2018).
breast tumor (3 papers, 2013 to 2019). "The positive correlation between the expression of CLEC10A ligands and patients’ prognosis as described here is supported by a recent study of a spontaneous breast tumor mouse model with a deletion of C1galt1 in mammary epithelium." (PMID 31455323, 2019). "Here we report that C1GALT1 mRNA and protein are frequently overexpressed in breast tumor tissues and high C1GALT1 expression correlates with higher histological grade and tumor stage." (PMID 25762620, 2015). "Transfection of C1GalT1 shRNA into MDA-MB-231 MUC1+ breast tumor cells decreased C1GalT1 protein level by 90% compared with untransfected cells." (PMID 24072600, 2013).
gastric tumor (3 papers, 2020 to 2025). "In addition, the protein levels of C1GALT1 showed a higher expression in gastric tumor tissues than in adjacent normal tissues." (PMID 38807485, 2024).
ovarian carcinoma (3 papers, 2020 to 2025). A malignant neoplasm originating from the surface ovarian epithelium. "The elevated expression of C1GALT1 was associated with poor survival in ovarian cancer patients." (PMID 32075174, 2020). "C1GALT1 knockdown resulted in decreased cell growth, migration, and sphere formation in a variety of ovarian cancer cell lines." (PMID 32075174, 2020).
pancreatic adenocarcinoma (3 papers, 2021 to 2025). "For example, knockout of C1GALT1 led to the truncation of O-glycosylation on MUC16 in pancreatic adenocarcinoma." (PMID 34452648, 2021). "Additionally, an in vivo study suggested that the absence of C1GalT1 in pancreatic adenocarcinoma is linked with increased Ki‐67 expression." (PMID 40548474, 2025). "To investigate C1GALT1 protein expression in paired pancreatic adenocarcinomas (PDACs) and their adjacent non-tumor tissues, we collected clinical samples from a tissue microarray (n = 27) (Biomax PA811) and the National Taiwan University Hospital (n = 99) (Taiwan)." (PMID 33420364, 2021).
colorectal tumors (2 papers, 2014 to 2021). "It was reported that excessive expression of C1GalT1 in colorectal tumour tissues was associated with invasion, metastasis, and poor survival." (PMID 34681197, 2021). "Here we showed that C1GALT1 was frequently overexpressed in colorectal tumors and is associated with poor survival." (PMID 24758762, 2014). "In conclusion, we found that C1GALT1 is overexpressed in colorectal tumors and its overexpression is associated with poor survival of patients with colorectal tumors." (PMID 24758762, 2014). "The results from immunohistochemistry of C1GALT1 indicated that 67.8% (59/87) of colorectal tumors showed higher C1GALT1 expression than their normal counterpart tissues." (PMID 24758762, 2014). "In this study, we observed that both C1GALT1 and PNA-staining T antigen are frequently overexpressed in colorectal tumors at all stages." (PMID 24758762, 2014).
laryngeal carcinoma (2 papers, 2021 to 2024). Carcinoma that arises from the laryngeal epithelium. "Higher resistant to X-ray treatment was also seen in the higher C1GalT1-expressing Hep-2max cells, whose integrin-β1 carry more TF carbohydrate structures, than the low C1GalT1-expressing Hep-2min laryngeal cancer cells." (PMID 34944925, 2021).
thyroid cancer (2 papers, 2024 to 2025). "Thyroid cancer was the only cancer type with a statistically significant difference between M0 versus M1 samples, with the M0 subgroup having higher mean C1GalT1 gene expression (7.91; n = 282) compared to the M1 subgroup (7.54; n = 8; p = 0.007837)." (PMID 40548474, 2025). "Meanwhile, we highlight the importance of the miR-141-3p/C1GALT1/GLUT1 regulatory axis during thyroid cancer progression." (PMID 38845937, 2024). "Overall, our study clarified that C1GALT1 was overexpressed in thyroid cancer cell lines and tissues." (PMID 38845937, 2024). "While this study identified significant differences in C1GALT1 expression levels between metastatic and non‐metastatic cancers only in thyroid cancer, these findings may be constrained by limited sample sizes in the M1 subgroups for other cancer types." (PMID 40548474, 2025). "However, the regulatory mechanisms of C1GALT1 in thyroid cancer (TC) is still unclear." (PMID 38845937, 2024). "However, the biological function and potential molecular mechanism of C1GALT1 in thyroid cancer have not yet been reported." (PMID 38845937, 2024). "However, the role of C1GALT1 in thyroid cancer remains unclear, and the pathogenesis has not been elucidated." (PMID 38845937, 2024).
Alzheimer disease (1 paper, 2025). A progressive, neurodegenerative disease characterized by loss of function and death of nerve cells in several areas of the brain leading to loss of cognitive function such as memory and language. "We subsequently confirmed decreased C1GALT1 and mucin-domain glycoprotein levels via staining in acutely isolated microvessels from brains of patients with Alzheimer’s disease compared with age-matched controls." (PMID 40011765, 2025). "C1galt1 was also selected for knockdown to better understand the effects of its downregulation in brain endothelial cells observed in both ageing and Alzheimer’s disease." (PMID 40011765, 2025).
atopic dermatitis (1 paper, 2024). "In the combined dataset, the expression of galactose-deficient IgA1-associated genes (including GALNT2, GALNT12, C1GALT1, C1GALT1C1 and ST6GALNAC2) were compared between atopic dermatitis patients and healthy controls." (PMID 39119579, 2024).
cervical cancer (1 paper, 2025). A primary or metastatic malignant neoplasm involving the cervix. "In cervical cancer, glioblastoma, and liver cancer, the differences in C1GalT1 expression between normal and tumor tissues were not statistically significant." (PMID 40548474, 2025).
colorectal adenocarcinoma (1 paper, 2014). The most common type of colorectal carcinoma. "Immunohistochemical analysis confirmed that C1GALT1 was up-regulated in colorectal adenocarcinoma cells compared with adjacent normal epithelial cells." (PMID 24758762, 2014).
ductal breast carcinoma (1 paper, 2015). "Data retrieved from public databases show that C1GALT1 mRNA expression levels are up-regulated in ductal breast carcinoma (n = 40) compared with normal (n = 7) (Oncomine)." (PMID 25762620, 2015).
endometrioid carcinomas (1 paper, 2023). "First, serous carcinomas showed significantly lower C1GALT1 protein expression compared with endometrioid carcinomas (median C1GALT1 expression = -0.37 vs. 0.385)." (PMID 36745330, 2023).
endometrioid tumor (1 paper, 2023). A benign, borderline, or malignant epithelial tumor of the female reproductive system characterized by the presence of glands and/or cysts lined by neoplastic cells that resemble endometrial cells. "C1GALT1 score varied across histologic types, with endometrioid tumors displaying the highest protein expression (median C1GALT1 IHC score = 200)." (PMID 36745330, 2023). "Second, a significant trend towards lower C1GALT1 expression in high grade tumors was also evident, in spite of this association being less obvious and non-significant when analyzing endometrioid tumors independently." (PMID 36745330, 2023).
gastric adenocarcinoma (1 paper, 2020). "Here, we showed that C1GALT1 high expression in gastric adenocarcinomas correlated with adverse clinicopathologic features and is an independent prognostic factor for poor overall survival." (PMID 32005975, 2020). "To better understand the mechanism by which C1GALT1 regulates gastric adenocarcinoma progression, we evaluated global gene expression in control and C1GALT1 knockdown AGS cells." (PMID 32005975, 2020). "From the Oncomine database, DErrico Gastric, Chen Gastric, and TCGA gastric showed that C1GALT1 mRNA expression was overexpressed in gastric adenocarcinoma compared with normal gastric mucosa tissue." (PMID 32005975, 2020). "In this study, we found that C1GALT1 was significantly overexpressed in gastric adenocarcinomas; and that C1GALT1 high expression correlated with adverse clinicopathologic features and is an independent prognostic factor for poor overall survival." (PMID 32005975, 2020). "Only 4% of cases exhibited lower C1GALT1 expression in gastric adenocarcinomas." (PMID 32005975, 2020). "Our immunohistochemical staining indicated that 80% (n = 25) of gastric adenocarcinoma tissues showed higher C1GALT1 protein levels than paired nontumor gastric tissues." (PMID 32005975, 2020).
glioblastoma (1 paper, 2025). The most malignant astrocytic tumor (WHO grade IV). "For instance, the MKI67 gene, a well‐established marker of cellular proliferation used widely in cancer grading and prognosis, showed significant correlation with C1GALT1 in nearly all tumor types evaluated, except for glioblastoma." (PMID 40548474, 2025). "Statistically significant differences in overall survival (OS) were observed between low and high C1GalT1 expression groups in lung, bladder, head and neck, testicular and liver cancers, and glioma/glioblastoma." (PMID 40548474, 2025).
glioma (1 paper, 2025). A benign or malignant brain and spinal cord tumor that arises from glial cells (astrocytes, oligodendrocytes, ependymal cells). "Similarly, in lower‐grade glioma, the low C1GalT1 expression group exhibited a markedly greater OS compared to the high expression group." (PMID 40548474, 2025).
Hyperammonemia (1 paper, 2022). An increased concentration of ammonia in the blood. "We demonstrated that silencing C1GALT1 could depress the IP3R1 expression, an effective strategy to inhibit the ammonia-induced upregulation of Ca2+ activity, thereby C1GALT1 and IP3R1 may serve as therapeutic targets in hyperammonemia of HE." (PMID 35164881, 2022).
kidney clear cell carcinoma (1 paper, 2025). "For kidney clear cell carcinoma, normal tissues had a higher median expression of C1GALT1 compared to tumor tissues (p = 0.009444 × 10−3)." (PMID 40548474, 2025). "Furthermore, kidney clear cell carcinoma, thyroid, breast, and prostate tumor tissues showed significantly lower C1GALT1 expression than normal tissues in both portals." (PMID 40548474, 2025).
liver cancer (1 paper, 2025). An epithelial or non-epithelial malignant neoplasm that arises from the liver. "In our study, most of the metastasis‐associated genes showed a positive correlation with C1GALT1 in prostate, breast, pancreas, bladder, and liver cancers, which was correlated with the previous studies." (PMID 40548474, 2025). "In lung, bladder, head and neck, and liver cancers, the low C1GalT1 expression group demonstrated statistically significantly better OS than the higher expression group." (PMID 40548474, 2025). "The PTPRD gene was positively correlated with C1GALT1 expression in kidney‐clear cell carcinoma and other cancers such as colon, head and neck, thyroid, prostate, breast, ovarian, liver cancers, and melanoma." (PMID 40548474, 2025). "However, in previous studies, higher C1GALT1 expression was seen in breast, prostate, ovarian, and liver cancers, opposite to our study." (PMID 40548474, 2025). "The TSC2 gene exhibited a positive correlation with C1GALT1 expression in pancreatic and liver cancers, while showing a negative correlation in colon, rectal, kidney‐clear cell, and melanoma cancers." (PMID 40548474, 2025).
melanoma (1 paper, 2025). A malignant, usually aggressive tumor composed of atypical, neoplastic melanocytes. "The expression levels of the RSF1 gene were positively correlated with C1GALT1 gene expression levels in all cancer types, including melanoma." (PMID 40548474, 2025).
meningioma (1 paper, 2024). A generally slow growing tumor attached to the dura mater. "In the GEO database, the respective mRNA expressions of C1GALT1, COSMC, C2GNT1, C2GNT2, and B3GNT6 was highly expressed in Grade I, Grade II, and Grade III meningiomas." (PMID 38274327, 2024). "Specifically, C1GALT1 and COSMC were highly expressed in both the primary benign and malignant meningioma cell lines, suggesting a high expression of core 1 (T antigen, Gal1GalNAc1) in meningiomas." (PMID 38274327, 2024). "The gene expression experiments demonstrated that mRNA expression of C1GALT1 and COSMC were highly expressed in both the primary benign and malignant meningioma cell lines." (PMID 38274327, 2024).
Parkinson disease (1 paper, 2024). A progressive degenerative disorder of the central nervous system characterized by loss of dopamine producing neurons in the substantia nigra and the presence of Lewy bodies in the substantia nigra and locus coeruleus. "Furthermore, the KEGG pathway analysis showed potential correlations between C1GALT1 and pathways including Parkinson’s disease, protein processing, ribosome, proteoglycans in cancer, proteasome, protein export and PI3K/Akt signaling pathway." (PMID 38662050, 2024).
psoriasis (1 paper, 2022). An autoimmune condition characterized by red, well-delineated plaques with silvery scales that are usually on the extensor surfaces and scalp. "This may suggest that the expression of the two enzymes may be regulated differently with the involvement of either both C1GALT1 and ST6GAL1 or exclusively ST6GAL1 for AD and psoriasis, respectively." (PMID 35784319, 2022).
rectal cancer (1 paper, 2025). A primary or metastatic malignant neoplasm that affects the rectum. "For colon and rectal cancer types, some metastasis‐associated genes were positively correlated, and some were negatively correlated with C1GALT1 in our study." (PMID 40548474, 2025).
testicular cancer (1 paper, 2025). A primary or metastatic malignant neoplasm that affects the testis. "On the other hand, in testicular cancer, the high C1GalT1 expression group showed better OS compared to the low expression group." (PMID 40548474, 2025).